PIK3CG (phosphatidylinositol-4,5-bisphosphate 3-kinase catalytic subunit gamma)
Diseases named in the same sentence as PIK3CG in open-access papers (continued):
Sharing a sentence is not in itself a finding about the gene and the disease.
dementia (1 paper, 2024). Loss of intellectual abilities interfering with an individual's social and occupational functions. "Four protective proteins (PLEK, DAPP1, CSK and CASP3) that decreased postinfection in the BLSA were significantly decreased in dementia cases in the ARIC study, with several other protective proteins (EIF4A1, DSG1, PIK3CG, PRKCB and LYN) showing similar trends." (PMID 39143319, 2024).
diabetic retinopathy (1 paper, 2017). "Besides, the VEGF signaling pathway played an important role in the diabetic retinopathy involved in multiple targets including PIK3CG, PTGS2, and VEGFA." (PMID 29051733, 2017).
endometrial adenocarcinoma (1 paper, 2017). "In contrast, PIK3CG (p.Ser931Cys) was altered only in the endometrial adenocarcinoma." (PMID 28103826, 2017).
hepatitis C (1 paper, 2020). "The top five degrees of the potential targets for the YCHD in the treatment of hepatitis C include PIK3CG, CASP3, BCL2, CASP8, and MMP1." (PMID 32050950, 2020). "There is no related research to show the PIK3CG is closely related to hepatitis C. Therefore, it is necessary to further explore the mechanism of the YCHD in modulating hepatitis C by regulating PIK3CG." (PMID 32050950, 2020).
injury (1 paper, 2023). Damage inflicted on the body as the direct or indirect result of an external force, with or without disruption of structural continuity. "Notably, PIK3CG, one of the hub genes, displayed high topological characteristic values, strongly suggesting its promise as a novel target for MEL‐evoked treatment of septic myocardial injury." (PMID 36684068, 2023).
ischemia (1 paper, 2017). A hypoperfusion of the BLOOD through an organ or tissue caused by a PATHOLOGIC CONSTRICTION or obstruction of its BLOOD VESSELS, or an absence of BLOOD CIRCULATION. "This study explores the associations between PIK3CG single nucleotide polymorphisms (SNPs, rs1129293 and rs17398575) and patient responsiveness to clopidogrel to evaluate the risks of ischemia in patients with coronary heart disease (CHD)." (PMID 28885323, 2017).
keratoconus (1 paper, 2023). A degenerative, structural disorder of the eye, characterized by a cone-shaped protrusion of the cornea. "Three variants in PIK3CG have been described in families affected by keratoconus." (PMID 37895187, 2023).
liver cancer (1 paper, 2021). An epithelial or non-epithelial malignant neoplasm that arises from the liver. "NR0B2 expression is conversely correlated with tumor-infiltrating B-cells, CD8+ T cells, and dendritic cells, as well as PIK3CA and PIK3CG gene expression in liver cancer tissues." (PMID 34055653, 2021). "In addition, NR0B2 expression negatively correlated with immune infiltration and PIK3CA and PIK3CG gene expression in liver cancer tissues." (PMID 34055653, 2021).
metastatic melanoma (1 paper, 2020). A melanoma that has spread from its primary site to another anatomic site. "The protein, PIK3CG, was present in many of these pathways and had increased gene expression in metastatic melanoma tissue from the cancer genome atlas data." (PMID 32891176, 2020).
metastatic tumors (1 paper, 2020). "PIK3CG protein levels were significantly increased in metastatic tumors in comparison to the primary by proteomics." (PMID 32891176, 2020). "PIK3CG is in the P2Y purigenic receptor signaling pathway and the protein level was upregulated in all three metastatic tumors as compared to the primary tumor." (PMID 32891176, 2020). "IHC confirmed no PIK3CG staining was present in the primary tumor and focally and weakly positive staining was present in all metastatic tumors." (PMID 32891176, 2020).
myocardial infarction (1 paper, 2019). Gross necrosis of the myocardium, as a result of interruption of the blood supply to the area, as in coronary thrombosis. "ACT and isoacteoside docked with phosphatidylinositol-4,5-bisphosphate 3-kinase, catalytic subunit gamma (PIK3CG), which has an important relationship with myocardial infarction." (PMID 31178740, 2019).
myopia (1 paper, 2024). "PIK3CG and PRKAR2B are significantly correlated with the susceptibility to myopia in chicks, suggesting the role of this locus in the susceptibility to myopia in the population." (PMID 38660258, 2024).
schwannoma (1 paper, 2020). A benign, usually encapsulated slow growing tumor composed of Schwann cells. "We found that upregulated genes PIK3CG, CSF1R, SPP1, and CCND1 and downregulated genes EGFR and VWF were significantly enriched in PI3K-Akt signaling pathway involved in VSs development, which can increase schwannoma cell proliferation, survival, and cell-matrix adhesion acting." (PMID 32733557, 2020).
squamous cell lung carcinoma (1 paper, 2024). A carcinoma arising from squamous bronchial epithelial cells. "Mutations in PIK3CG have been associated with shorter survival in squamous cell lung cancer and increased mutation frequencies in brain metastases compared to primary tumors." (PMID 39950101, 2024).
unstable angina (1 paper, 2020). "The results of this study suggest a lack of association between GP6 (rs1671152), PEAR1A (rs12566888), MRVI1 (rs7940646), PIK3CG (rs342286), JMJD1C (rs10761741), SHH (rs2363910), and unstable angina." (PMID 33076381, 2020). "In this study, we examined the associations between polymorphisms in GP6 (rs1671152), PEAR1A (rs12566888), MRVI1 (rs7940646), PIK3CG (rs342286), JMJD1C (rs10761741), and SHH (rs2363910) and unstable angina." (PMID 33076381, 2020).
tumor (136 papers, 2004 to 2026). "Recent studies highlight the pivotal role of PIK3CG, an emerging immune checkpoint, particularly involving tumor-associated macrophages (TAMs)." (PMID 39877641, 2025). "Here the authors report a gene-editing delivery system using functionalized nanovesicles derived from E. coli protoplasts to encapsulate Cas9-sgRNA ribonucleoprotein for the selective targeting of Pik3cg in tumor associated macrophages." (PMID 38296939, 2024). "ARID2, NF1, and PIK3CG mutations are associated with poor tumor differentiation and the epithelial–mesenchymal transition." (PMID 34158601, 2021). "Moreover, the deficiency of PIK3CG protects anthracycline‐induced cardiotoxicity and decreases tumor growth." (PMID 36684068, 2023). "Compound 17, which exhibited cytotoxicity against PANC−1 cells, was linked to 55 targets, including key targets such as EGFR, AKT1, CDK1, CDK2, MMP9, PIK3CG, and TERT, closely associated with tumour cell proliferation, migration, and apoptosis." (PMID 41006588, 2025). "Future research requires a deeper understanding of the differential expression and functional characteristics of PIK3CG in tumor and normal cells, and the development of more selective targeted drugs to reduce damage to normal cells." (PMID 40070829, 2025). "Predominantly expressed in macrophages, PIK3CG displayed a marked contrast to its lower expression levels in tumor cells." (PMID 39468696, 2024). "Evidence suggests that PIK3C2G and its related gene PIK3CG contribute to tumor progression and metastasis." (PMID 39950101, 2024). "Meanwhile, three targeted genes (AKT1, MTOR and PIK3CG) of these drugs showed significant upregulation in SLC12A5‐low tumour." (PMID 38685685, 2024). "PIK3CG plays a role in influencing cancer progression and the tumor microenvironment, particularly through immune cell signaling." (PMID 39850811, 2024). "A significant increase was observed in single-nucleotide variants in the genes ATM, ATR, BRCA1, LRP1B, MAP2K1, PIK3CG and ZNF217 in addition to BRAF, KRAS, NRAS and EGFR among tumours receiving prior anti-EGFR." (PMID 37569598, 2023). "While PI3K p110γ inhibition in host immune cells did not significantly lower tumor burden or influence lymph node metastasis, the immune response in the tumor microenvironment was substantially modulated in Pik3cg−/− mice." (PMID 33668795, 2021). "We also observed a significant upregulation of PD-L1 among Pik3cg−/− G-MDSCs, M-MDSCs, and M2s at the primary tumor site and metastasized lymph nodes." (PMID 33668795, 2021). "Following ESC treatment, while the PIK3CG gene was downregulated and the p21gene was upregulated in tumor tissue, whereas the PIK3CG gene was upregulated and the p21 gene was downregulated in skin tissues." (PMID 31367256, 2019). "PIK3CG induces a transcription process that promotes immune suppression tumor growth and inflammation." (PMID 30618763, 2018). "In addition, further exploration is needed to investigate the interaction between PIK3CG and other signaling pathways, as well as the resistance mechanism of tumor cells to PIK3CG targeted therapy, to provide a basis for optimizing treatment plans." (PMID 40070829, 2025). "Targeting PIK3CG with specific inhibitors, in combination with other pathway modulators, could effectively disrupt these processes and limit tumor progression." (PMID 39850811, 2024). "In poorly immunogenic head and neck squamous cell carcinoma mice models, the genetic inhibition of Pik3cg, the gene encoding for the PI3Kγ catalytic subunit, did not alter tumor growth nor lymph node metastasis." (PMID 36765741, 2023). "It is possible that drugs inhibiting both CSNK21A and PIK3CG may have synergistic anti-tumor activity." (PMID 22219723, 2011). "This requires glucose uptake and energy sources for normal cellular response to stress and tumor growth, syndrome development, vascular changes, and megalocephaly (e.g., PIK3R1; PIK3CA; PIK3CG; PIK3CD; PIK3CB; PIK3R3; PIK3R2; PIK3R5; PIK3R6)." (PMID 41010006, 2025).
tumor (continued). "Overexpression of PIK3CG in TNBC suggests its involvement in enhancing cancer cell proliferation and resistance to apoptosis, contributing to tumor aggressiveness." (PMID 39850811, 2024). "In the tumor samples, F2, GLS2, IDO2, and PLAUR were shown to be significantly upregulated, while GNG7, PIK3CG, and ST3GAL6 were significantly down-regulated." (PMID 33619235, 2021). "We observed significant increases in IL-17 expression by both CD4+ and CD8+ T-cells in the spleens and lymph nodes of tumor-bearing Pik3cg−/−, though not in the tumor." (PMID 33668795, 2021). "PIK3CG is highly expressed in TME and it prevents T cell mediated tumor elimination." (PMID 33619235, 2021). "Despite a lack of difference in tumor growth and metastasis, it was surprising to observe increased CD8+ T-cell tumor infiltration in tumor-bearing Pik3cg−/− mice, a phenotype generally associated with improved prognosis in human HNSCC." (PMID 33668795, 2021). "Moreover, LGG tumors with CD302 or FABP5 overexpression highly expressed some oncogenes, including GPR65, PIK3CG, CHI3L1, and RAB36, which were reported to promote tumor growth and metastasis." (PMID 32775301, 2020). "In addition, PIK3CG and BIRC3 were also found in PPI network and correlated with immune cells infiltrating in tumor microenvironment." (PMID 32010618, 2019). "These antitumor effects were attributed to suppression of PIK3CG in macrophages leading to suppression of cytotoxic T cells and not due to decreased PIK3CG in tumor cells." (PMID 31112530, 2019). "Based on previous literature and our study, we speculated that psoralen inhibited the proliferation and migration ability of tumor cells, promoted apoptosis, and blocked the cell cycle by reducing the expression levels of four genes: JAK2, PIK3CA, PIK3CB, and PIK3CG." (PMID 36065261, 2022). "We found that in tumor-bearing Pik3cg−/− mice, PD-1 expression was significantly higher in both CD4+ and CD8+ cells of the lymph nodes and spleens, though we did not observe this difference in the tumor microenvironment." (PMID 33668795, 2021).
cancer (130 papers, 2007 to 2026). A tumor composed of atypical neoplastic, often pleomorphic cells that invade other tissues. "Mutations in p110γ encoded by PIK3CG in cancer are less frequent, however, they can still provide insight into regulatory mechanisms that control activity." (PMID 37417733, 2023). "There have also been numerous reports of overexpression and single-nucleotide variants in PIK3CG linked to cancer development in multiple tissues." (PMID 33661099, 2021). "Some of these may have novel roles in relation to cancer and/or the LP-184 mechanism of action, while some have been previously reported to play roles in cancer malignancy – e.g., PIK3CG which is tightly associated with growth and migration in several cancers." (PMID 33653269, 2021). "Among 38 probes, 27 were annotated in GO: 6 were for the major lymphoid-restricted membrane protein (JAW1), 2 for the B-cell CLL/lymphoma 7A (BCL7A), 2 for phosphoinositide-3-kinase, catalytic, gamma polypeptide (PIK3CG) and 2 for cancer susceptibility candidate 1 (CASC1)." (PMID 17888167, 2007). "These insights provided a robust foundation for future investigations into the role of PIK3CG in cancer lymph node metastasis." (PMID 39468696, 2024). "PIK3CG activation switches on immune stimulation or suppression in cancer and acute/chronic inflammation." (PMID 34612148, 2021). "MiR-1976 knockdown promoted epithelial–mesenchymal transition (EMT) and cancer stem cell (CSC) properties by targeting PIK3CG in TNBC metastasis." (PMID 32620748, 2020). "PIK3CG is considered as a cancer-promoting gene in a variety of tumors, and it has been reported that PIK3CG promoted metastasis and invasion." (PMID 32620748, 2020). "Various cancer types have been shown to carry druggable targets for mTOR inhibitors, including mutations in MTOR, TSC1, TSC2, NF1, PI3KCA, PIK3CG, STK11, and RHEB." (PMID 31443247, 2019). "Class I PI3K isoforms are relevant for cancer, i.e., p110α (encoded by the PIK3CA gene), p110β (PIK3CB gene), p110γ (PIK3CG gene), and p110δ (PIK3CD gene)." (PMID 30832253, 2019). "We selected those genes with functions known to be associated with cancer of which there were 12—SNVs: NOTCH2, PIK3CG, IL2RB, BAI3, FREM2 and RERE; indels: UTRN, CDHR3, NCOA5, CABYR, HOTAIR and FOLH1." (PMID 26017033, 2015). "Similarly, PIK3CG was up-regulated in CSS-H tumors in 11 cancer types, and its expression was correlated with the sensitization of 60 anti-cancer drugs." (PMID 39822281, 2025). "Similarly, PIK3CG and mTOR levels increased sharply, suggesting a potential role of miRNA regulation in driving protein expression, which intensifies with cancer aggressiveness." (PMID 39850811, 2024). "Three frameshift mutations in cancer genes were lost in the PDX tumors: HGF, SPEN, and PIK3CG." (PMID 33602919, 2021). "Nevertheless, proteins p100β, p100δ, and p100γ are also capable of inducing oncogenic transformation in their wild-type form, in line with the fact that PIK3CB, PIK3CD, and PIK3CG are generally amplified or overexpressed, but not mutated, in cancer." (PMID 32033478, 2020). "The network pharmacology analysis showed that quercetin is involved in mediating cancer-related pathways, PI3K-Akt pathway, and Ras pathway to interfere with IPF by acting on AKT1 and PIK3CG." (PMID 40678729, 2025). "Interestingly, positively correlated loci represented cancer driver genes (MYC, PRKCD, RB1, CDK6), molecules involved in immune response (MALT1, PIK3CG), as well as cellular and hormonal signaling (HGF, PTPN13, IGF1, SMAD1, ESR1, CTGF)." (PMID 34368147, 2021).
cancer (continued). "We performed RT-qPCR and confirmed the differential expression of several cancer driver genes: increased mRNA expression of oncogenes MYC and PIK3CG, as well as decreased expression of tumor suppressor genes CDKN1A and EPHA2, was observed in the H2BE76K mutant cells." (PMID 33548228, 2021). "Additionally, Gzmb, an effector molecule involved in CD8+ killing of cancer cells, and Cxcl9, a chemokine important to CD8+ recruitment, were both highly elevated in the tumors of Pik3cg−/− mice compared to WT mice." (PMID 33668795, 2021). "Because the PI3K pathway is a known cancer pathway and one with relevance in ccRCC, we tested whether SLINKY knockdown affected PIK3CG expression." (PMID 28423633, 2017). "In addition, several hits, including PLK1, PRKAA1 (or AMPK), PIK3CG and ERBB3 have also been previously shown to mediate cancer cell survival and growth, independently validating the results of our screen." (PMID 27192118, 2016).
cardiovascular disease (5 papers, 2014 to 2023). "rs17398575, rs17477177, and rs342286 are located near PIK3CG and were associated with cardiovascular diseases risk." (PMID 29867955, 2018). "PI3Kγ/p110γ, also known as PIK3CG, is a key regulator molecule in the pathological process of inflammation and oxidation, and thus plays a critical role in a variety of cardiovascular diseases." (PMID 36684068, 2023).
infection (4 papers, 2018 to 2024). The state of being infected such as from the introduction of a foreign agent such as serum, vaccine, antigenic substance or organism. "For other types of infection, weak correlation was observed in severe influenza A infection, and moderate correlation between PIK3CG and NDG expression was observed in H1N1 infection." (PMID 38399976, 2024). "Data revealed that the expression of Pik3cg (P = 4.0E-3; unpaired t-test) and Pik3cd (P = 7.4E-6; unpaired t-test) genes, but not Pik3ca, are upregulated in the heart tissue of T. cruzi-infected mice 18 days post infection (dpi)." (PMID 29666415, 2018).
adenocarcinoma (2 papers, 2016 to 2023). A common cancer characterized by the presence of malignant glandular cells. "The KMT2D, GNAS, EP300, GRM3, and PIK3CG mutations were all significantly higher in patients with squamous than those with adenocarcinoma (P = 0.0066, P = 0.019, P = 0.0075, P = 0.017, and P = 0.0075, respectively)." (PMID 37301854, 2023).
neurological disease (2 papers, 2014 to 2021). "They include characteristic genes, Prnp, Cct4, Vegfd (Figf), Map9 (Mtap9), Pik3cg, Zfand5, Endog, and Hbq1, which are reportedly associated with AD, CJD, and/or related neurological disorders." (PMID 34959983, 2021).
hematological malignancies (1 paper, 2025). "Raman spectroscopy combined with multi-omics techniques has broad application prospects in the diagnosis of hematological malignancies, and the identification of IL15 and PIK3CG as potential therapeutic targets also provides new ideas and directions for the treatment of these diseases." (PMID 40070829, 2025). "In hematological malignancies, the PI3K signaling pathway is often abnormally activated, and upregulation of PIK3CG may be one of the important reasons for this abnormal activation." (PMID 40070829, 2025).
PIK3CG also shares sentences with these, for which no sentence is quoted: gastric cancer (7 papers); glioma (7); Insulin resistance (7); thyroid cancer (6); lymphoma (4); COVID-19 (3); diffuse large B-cell lymphoma (3); head and neck squamous cell carcinoma (3); hepatitis B (3); Immunodeficiency (3); osteoporosis (3); thymoma (3); acute lymphoblastic leukemia (2); Alzheimer disease (2); Astrocytoma (2); brain tumors (2); cardiac hypertrophy (2); cervical cancer (2); coronary artery disease (2); intrahepatic cholangiocarcinoma (2); Kaposi's sarcoma (2); ovarian endometriosis (2); RASopathies (2); schizophrenia (2); small cell lung carcinoma (2); squamous carcinoma (2); triple-negative breast carcinoma (2); acne (1); acute pancreatitis (1); adenocarcinoma of the lung (1).
A further 86 diseases each share a sentence with PIK3CG in 1 paper.